CCND1 (cyclin D1)
Diseases named in the same sentence as CCND1 in open-access papers (continued):
Sharing a sentence is not in itself a finding about the gene and the disease.
tumor (continued). "Increased interaction between β-TrCP and Cyclin D1 was shown to promote Cyclin D1 protelysis in LNCap cells with exposure of peroxisome proliferator-activated receptor-γ (PPARγ) agonist STG28 and thereby contributed to its anti-tumor activity." (PMID 27854312, 2016). "Since cyclin D1 over expression in HCC is mediated by the IL-6-STAT3 axis, we also determined the expression of phosphoSTAT3 in tumor tissue among different groups." (PMID 27626063, 2016). "The protein expression levels of cyclin D1, CDK4, cyclin E, CDK2, and Ki-67, a biological tumor marker that indicates changes in tumor proliferation, were reduced in the shVCP-transfected HCT116 cells, and increased in the lenti-VCP transfected RKO cells." (PMID 27344168, 2016). "IHC analysis of ER maleate treated tumor tissues showed a decrease in PLK1, Syk and Cyclin D1 expression, demonstrating that our in vitro findings were reproduced in vivo as well." (PMID 26934445, 2016). "To corroborate the role of cyclin D1 and CDK4 in the suppression of tumour growth of GC by Tspan5, we reconstituted the expression of cyclin D1 and CDK4 in Tspan5-overexpressing tumour cells." (PMID 27223087, 2016). "IGFBP6 knockdown activated the GSK3β/β-catenin/cyclin D1 pathway and enhanced CNE2 tumor cell growth and metastasis in a mouse model." (PMID 27623076, 2016). "As a consequence, it is concluded that C3G activity on tumor growth inhibition was probably through KLF6-mediated p21 induction, by disruption of the Cyclin D1 and CDK4 interaction, thus blocking the cell cycle." (PMID 27690088, 2016). "We also measured the expression of Ki67, CCND1 and CCND2 in xenograft tumor tissues using immunohistochemistry." (PMID 27494902, 2016). "IPMN, accordingly, showed intermediate expression of BCL9L, but instead demonstrated a high expression of the cyclin D1 inhibitor INPP5D, possibly contributing to the better prognosis of this neoplasia compared to PDAC." (PMID 27539223, 2016). "Meanwhile, E2F1 silencing inhibited tumor cell growth and invasiveness, accompanied by markedly decreased binding of E2F1 at CCND1 and CCNE1 gene promoters in ARID2-depleted cells." (PMID 27351279, 2016). "We also checked the expression of Cyclin D1, as a common downstream effector of JAK/STAT and PI3KCA/AKT pathways, inducer of chemoresistance in many tumor types and essential for cell cycle progression." (PMID 27517495, 2016). "Consistently, previous studies have revealed multiple targets for miR‐16 including BCL2, CCND1 and WNT3A 17, 18, 19, 20, which are involved in tumour cell apoptosis or cell‐cycle regulation; and thus, directly regulate tumour growth." (PMID 27241533, 2016). "A tumor suppressor miRNA, miR-34a-5p, targeted several critical cancer genes, including CDK6, CCND1, CCNE2, E2F3 in the cell cycle pathway and VEGFA in the angiogenesis pathway." (PMID 27329603, 2016). "We report here that cyclin D1 expression increases the expression of ICAM1, and the synthesis of pro-inflammatory chemokines IL8, IP10, and RANTES, all able to alter the tumor microenvironment." (PMID 27286258, 2016). "miR-1296 overexpression results in downregulation of CCND1, suppression of the proliferative ability of TNBC cells, and induction of tumor cell apoptosis." (PMID 26799586, 2016).
tumor (continued). "SGI‐1776, as a first-generation inhibitor, has high anti-tumour activity in vivo and in vitro by inhibiting FLT3, cyclin D1, MCL, Myc and Pgp." (PMID 27596051, 2016). "We found a statistically significant correlation between HOXA1 and cyclin D1 expression (r = 0.476, P < 0.001), and HOXA1 and cyclin D1 expression were detected in the same location of one tumor specimen." (PMID 26791264, 2016). "The qRT-PCR based panel of MYC, MYCN, CCND1, CCND2, EGFR and FNDC3A was successful in detecting neoplasia with an overall accuracy of 54 % in S-CRN compared to that of 29 % in UC neoplastic samples." (PMID 27080994, 2016). "The suppression of Nischarin and LKB1 in these cells resulted in increased phosphorylation of PAK1 and LIMK1, and upregulation of Cyclin D1 and CDK4 expression, resulting in enhanced cell migration and tumor growth." (PMID 25695373, 2015). "Considering the expression of only p27 and cyclin D1, apart from other markers, DFS was significantly worse for those patients whose tumor had unfavorable expression levels of both markers: (0–1 vs. 2): 65% vs. 17%, respectively (p = 0,002) (Table." (PMID 26834523, 2015). "Immunohistochemical staining of tumour tissue sections was also performed to detect expression of CDK8, β-catenin, and cyclin D1 in vivo." (PMID 26286725, 2015). "Nodal disease values were imputed adjusting for tumor size, the PPP2R2A (B55α)/Cyclin D1 phenotype and HER2 status." (PMID 25879784, 2015). "In contrast, tumour sections from the miR-101-treated mice exhibited only weak expression of cytoplasmic CDK8, β-catenin, and cyclin D1." (PMID 26286725, 2015). "We also analyzed protein expression levels of Cyclin D1, which coordinates with c-MYC in tumor initiation and progression." (PMID 26046375, 2015). "Intra-tumor heterogeneity was found in the primary tumors of 9 of 19 (47.3%) cancers with HER2, 8 of 17 (47.0%) cancers with CCND1, 5 of 7 (71.4%) cancers with EGFR, and 23 of 27 (85.2%) cancers with MYC amplification." (PMID 25649416, 2015). "We found that levels of molecules cyclin D1, CDK4, E2F1 and PCNA were increased significantly in the tumor lysates of metformin administered mice as compared to control, while p21 level was diminished." (PMID 26484566, 2015). "Our data reveal a novel molecular mechanism by which cyclin D1 expression directly targets the UPR, enhancing the response to bortezomib in MM tumor cells, as highlighting by clinical observations." (PMID 25881299, 2015). "miR-145 down regulates HIF-2α by targeting its 3’-UTR, and by decreasing the level of this transcription factor, repressed expression of downstream genes cyclin D1, VEGF, and MT1-MMP, and via this means, tumor cell growth, invasion, and metastasis." (PMID 26204513, 2015). "As expected, we found that Cyclin D1 and CDK6 were downregulated in vivo by miR-211 and that EOC tumor growth was reduced significantly by miR-211 overexpression." (PMID 25889927, 2015). "The relative expression of the genes Bmi-1, CCND1, and CDC6 was significantly increased in samples from all the tumor grades analyzed, and grade IV tumors were the most frequent." (PMID 26317630, 2015). "Moreover, an elevated Cyclin D1 expression has been associated with higher tumor size, lymph node commitment and poor prognosis; interestingly, we have seen that invasive clones of a tongue SCC cell line presented increased levels of cyclin D1 when compared to its noninvasive counterpart." (PMID 26449430, 2015). "Another possible explanation is the common function of the simultaneously amplified genes of 11q13 (CTTN, FADD, CCND1, and FGF4) in tumor growth and invasion." (PMID 26194878, 2015).
tumor (continued). "Immunohistochemical analysis showed that tumors from leptin-treated mice exhibited higher number of tumor cells showing increased expression of MTA1, Wnt1, β-catenin and cyclin D1 as compared to tumors from vehicle-treated group." (PMID 26036628, 2015). "NF-κB plays a critical role in the regulation of proteins involved in the cell survival (Bcl-2, XIAP), proliferation (cyclin-D1), invasion (MMP-9, RANKL), angiogenesis (VEGF), and inflammation (COX-2, TNF-α), all contribute to the tumor progression." (PMID 26487364, 2015). "Two major target genes of NF-κB, cell cycle cyclin D1 and Vascular Endothelial Growth Factor (VEGF), are known to play a vital role in tumor progression." (PMID 26839513, 2015). "The 11q13 amplicon contains Cyclin D1 which is a known oncogene but also FGF19, FGF23 and ANO1 which are tumour promoting genes." (PMID 28943626, 2015). "In the present study, the data revealed that the compounds Ad23 and Af23 suppressed the phosphorylation of FGFR1 in H460 tumor tissues, thereby inhibited the downstream phosphorylation of ERK and AKT, and reduced the expression of BCL-2, COX-2, and Cyclin D1." (PMID 25880284, 2015). "In the present study, RTA 408 reduced cyclin D1 and increased CDKN1A protein levels in all eight tumor lines." (PMID 25897966, 2015). "Univariate analysis indicated that tumor size, TNM stage, nodal metastasis, the ratio of metastasized nodes to retrieved nodes, cyclin D1 immunostaining and SUVmax correlated with survival (P < 0.05)." (PMID 26689966, 2015). "Our results showed that in tumours of curcumin-treated group, there were significant reductions in the expression of PECAM-1, cyclin D1, and p65 compared to the control group." (PMID 25879038, 2015). "Co-activation of both SHH and CXCR4 resulted in higher expression of cyclin D1, while CXCR4 antagonism, resulted in decreased cyclin D1 expression and also blocked maximal MB tumor growth." (PMID 26512695, 2015). "Among target genes of TCF/LEF family, cyclin D1 and c-myc are responsible for the decision between proliferation and apoptosis in the cells, and matrix metalloproteinase-7 (MMP-7) is related with tumor metastasis." (PMID 26289446, 2015). "In fact, miR-16 has been reported to act as a tumor-suppressive miRNA in many cancer types, and multiple apoptosis-related genes are targeted by miR-16, including BCL-2, CCND1, CCND3, and CCNE1." (PMID 26031775, 2015). "Tumors from HNK+leptin treatment group showed very low percentage of tumor cells showing expression of MTA1, Wnt1, β-catenin and cyclin D1 providing physiological relevance to our in vitro findings." (PMID 26036628, 2015). "Higher percentage of tumor cells showed increased expression of MTA1, β-catenin and cyclin D1 in HFD group as compared to ND group." (PMID 26036628, 2015). "CCND1 at 11q13, a well-documented region of high amplification, represented the gene most commonly involved in HFA in our dataset, across multiple tumour types." (PMID 25889064, 2015). "Metoformin inhibited the proliferation and tumor growth of RCC cell lines 786-O and OS-RC-2, also with down-regulating of cyclin D1 expression and cell cycle arrest." (PMID 25322986, 2014). "When experiments were terminated for tumor harvesting, the NCI-N87-derived cancer that was infected with Virus_CCND1 exhibited a 45.6% (P < 0.01) and a 37.5% (P < 0.05) decrease in volume by comparison with Saline and Virus_Scramble, respectively." (PMID 24618206, 2014). "Other examples include MCM10 and CCND1 also targeted by miR-199a-5p, PBK, that promotes tumour cell proliferation through p38 MAPK activity that is targeted by miR-28-5p and cyclin genes CCND1 and CCND2 targeted by miR-150." (PMID 25200074, 2014). "Furthermore, six studies reported data on tumor size, sixteen studies reported data on T category, fourteen studies reported data on N category, nine studies reported data on distant metastasis, eighteen studies reported data on histology and their relationship with cyclin D1 expression." (PMID 24728073, 2014).
tumor (continued). "A xenograft assay in nude mice finally proved the potent inhibitory effects of curcumin on tumor growth and the pro-proliferative YAP/TAZ/KLF5/cyclin D1 axis." (PMID 25170806, 2014). "We therefore measured the effects of embelin on the expression of cell cycle proteins (Cyclin D1, CDK-2, and CDK-6), and Bcl-2 family members (Bcl-2, and Bax) in tumor tissues by Western blot analysis and immunohistochemistry." (PMID 24694877, 2014). "In the present study we demonstrate that dietary AXT inhibits tumour progression based on abrogation of the JAK/STAT3 pathway and its downstream targets cyclin D1, MMP-2, -9, and VEGF in the HBP carcinogenesis model." (PMID 25296162, 2014). "These include caveolin 1 [which directly binds DLC1 and contributes to its tumor suppressive roles], CDKN1B [which is an inhibitor of and directly binds to CDK6], and cyclin D1 [which forms a complex with CDK6]." (PMID 25425654, 2014). "Tumours were classified regarding invasiveness, tumour size, axillary lymph node status, Nottingham grade, tumour proliferation (Ki67), HER2, cyclin D1 and p27, WHO histological type and hormone receptor status." (PMID 24708573, 2014). "Ivermectin also diminished the protein levels of CYCLIN D1, a direct TCF target and oncogene, in both HT29 and H358 tumor cells (Fig4D)." (PMID 25143352, 2014). "These include wild-type neu/ErbB2 transgenic mice with tumor latency of 30 to 52 weeks, and MMTV-cyclin D1 mice with approximately 70 weeks as mean age at onset." (PMID 25516216, 2014). "The miR-15a/16 cluster, for example, is well known to act as a tumor suppressor by targeting multiple oncogenes, including BCL2, MCL1, CCND1 and WNT3A, whereas the miR-17/92 cluster is recognized as an oncogene." (PMID 24520312, 2014). "We then assessed whether the expression of Bcl-2, Bcl-xL, survivin, p21 and cyclin D1 correlates with various clinical and pathologic parameters, including gender, location and size of the tumor, lymph node metastasis, histologic grade, depth of tumor invasion/clinical stage and overall survival." (PMID 25438156, 2014). "Molecular studies done on excised tumor (A549) tissue suggested that BBR in SD form resulted in a significant decrease in the survivin, Bcl-2, cyclin D1, MMP-9, HIF-1α, VEGF and CD31 expressions." (PMID 24614362, 2014). "Knocking down endogenous CTGF expression elevated the activiation of pRB(ser 780), an oncogenic cell cycle regulator including CCND1 and E2F1, and suppressed the expression of tumor suppressors including p15 and p21." (PMID 23755163, 2014). "Downregulation of the cell cycle regulatory proteins cyclin D1 and PCNA, biomarkers of the malignant phenotype and tumor progression with increased expression of p21 the most potent CDK inhibitor, underscore the antiproliferative effects of astaxanthin." (PMID 25296162, 2014). "Dysregulation of β-catenin and other Wnt components leads to activation of Wnt target genes, including c-myc, cyclin D1, and MMP-9, and the enhancement of tumor formation." (PMID 25471741, 2014). "The protein levels of Cyclin E1, Cyclin D3, Cyclin D1,Cyclin A2, CDK2 and CDK4 were significantly decreased in tumor tissues harvested from miR-188 injected mice." (PMID 25304455, 2014). "Next, we want to confirm the inhibitory effects of curcumin on tumor growth and the YAP/KLF5/cyclin D1 axis in a nude mice xenograft model." (PMID 25170806, 2014). "Luminal A tumours tend to be low grade tumours that are characterised by over expression of ER-activating genes including LIV1, CCND1, FOXA1, XBP1, GATA3 and Bcl-2." (PMID 24392136, 2014). "Oral administration of ferulic acid at 40 mg/kg body weight to hamsters treated with DMBA not only completely prevented the tumor formation, but also suppressed PCNA and cyclin D1 expression." (PMID 28239123, 2013).
tumor (continued). "miR-16 can act as a tumor suppressor through pathways involving BCL2 and CCND1, validated targets (here also anti-correlated)." (PMID 23405235, 2013). "The protein levels of Cyclin D1, Pro-Caspase-3, Bcl-2, MMP2 and MMP9 in tumor extracts were examined by western blot." (PMID 23874680, 2013). "Although investigation into the mechanisms by which BRD4 influences cyclin D1 expression was beyond the scope of this paper, further investigation of this interaction could be of clinical relevance, considering the importence of the cyclin D family in tumor maintenance." (PMID 24231268, 2013). "Tumors of the head and neck present aggressive pathological behavior in patients due to high expression of CDK/CCND1 proteins." (PMID 23414419, 2013). "To further explore the mechanism of EESP’s anti-tumor activity, we performed RT-PCR and IHS analyses to respectively examine the mRNA and protein expression of Bcl-2, Bax, Cyclin D1, CDK4, VEGF-A and VEGFR-2 in CRC mice." (PMID 23800091, 2013). "In this study we examined the contribution of important HIF-responsive genes such as VEGF, CCND1, ANGPTL4, EGLN3, ENO2, GLUT1 and IGFBP3 to tumor growth in a xenograft model using immune-compromised nude mice." (PMID 24260413, 2013). "Histologically, inhibition of AKT not only decreased the tumor features including hemorrhagic foci and neovascularization, but also reduced the levels of VEGF, b-FGF, and cyclin D1." (PMID 23301033, 2013). "Notably, aberrant expression of certain WNTs, inactivating mutations of the APC and AXIN tumor suppressors and oncogenic activating mutations of β-catenin (CTNNB1) have been shown to contribute to cell transformation via deregulation of genes, such as c-MYC and CCND1 (cyclin D1)." (PMID 24260410, 2013). "Dysregulation of β-catenin and other Wnt components lead to nuclear localization of β-catenin, activation of Wnt target genes, including c-Myc, cyclin D1, cyclooxygenase-2, matrix metalloproteinase-7, gastrin, and ITF-2 and enhance tumor formation." (PMID 23646150, 2013). "AMA-treated tumor spheroids demonstrated suppressed expression levels of β-catenin and its signaling components including TCF-4, NF-κB, and cyclin D1, which provides a partial explanation of how AMA was able to inhibit tumor spheroid formation." (PMID 23840269, 2013). "As cyclin D1 is a target of let-7e-5p, the repression of let-7e-5p expression by JARID1B was suggested to stimulate tumor cell proliferation by allowing cyclin D1 expression and hence cell cycle progression." (PMID 24257477, 2013). "More importantly, metformin markedly decreased the expression of cyclin D1 and increased the number of apoptotic cells in a xenograft model, showing the suppression of OSCC tumor growth in vivo." (PMID 23151022, 2012). "They aimed to correlate cell line and animal data with primary tumor samples, because there had been previous contradictions regarding the relationship between SMARCB1, p16INK4A, and cyclin D1." (PMID 22988546, 2012). "Both in vitro and in vivo studies have found that cyclin D1 overexpression can inhibit the differentiation of myoblasts and intestinal epithelial cells, thus raising the possibility that cyclin D1 overexpression may play a role in the inhibition of tumor cell differentiation in some cell types." (PMID 22336657, 2012).